ATP7A (ATPase copper transporting alpha)
Diseases named in the same sentence as ATP7A in open-access papers (continued):
Sharing a sentence is not in itself a finding about the gene and the disease.
breast carcinoma (continued). "In brief, our results showed miR‐148a could accelerate chemotherapy induced‐apoptosis in breast cancer cells by inhibiting ATP7A expression." (PMID 32508020, 2020). "Meanwhile, the breast cancer cells treated with TM, as an active copper chelating agent, could achieve comparable cytotoxicity yielded from ATP7A knockdown." (PMID 32508020, 2020). "In this current study, we identified knocking‐down ATP7A could enhance cytotoxicity treatment of cisplatin in breast cancer cells." (PMID 32508020, 2020). "Next, we assessed whether breast cancer cells knocked‐down ATP7A with cisplatin treatment produced more DNA damage than cisplatin alone." (PMID 32508020, 2020). "Then, we investigated whether miR‐148a‐3p affected the cisplatin resistance on breast cancer cell lines through reducing ATP7A." (PMID 32508020, 2020). "Accordingly, immunofluorescence staining revealed partial colocalization of ATOX1, ATP7A and LOXPP, c, at the lamellipodial borders of breast cancer cells." (PMID 40721800, 2025). "We identified 13 members of the copper transport system associated with the occurrence, progression, and mortality of breast cancer, including SLC31A1, DMT1, ATP7A, ATP7B, MTs, GSH, ATOX1, CCS, COX17, SCO1, SCO2, and COX11." (PMID 39676279, 2024). "According to a study applying CRISPR/Cas9 to silence ATP7A,the activity of LOX was inhibited in breast cancer and lung cancer cell lines,suppressing these tumor cell growth and migration." (PMID 36925927, 2023). "Copper pathways, including the ATOX–ATPase copper transporting Alpha (ATP7A)–lysyl oxidase (LOX) pathway, facilitate cancer cell metastasis, and inhibiting this pathway has been shown to impede breast cancer metastasis in vivo." (PMID 37886979, 2023). "Since DLAT, SLC31A1, ATP7A and ATP7B were all found to be related to prognosis in breast cancer, a combined prognostic model aggregating more cuproptosis-related genes and clinical features is expected in future." (PMID 35996075, 2022). "We found that genes DLAT, SLC31A1, ATP7A and ATP7B were significantly related to the overall survival (OS) of breast cancer patients in univariate Cox regression analysis." (PMID 35996075, 2022). "Antioxidant 1 copper chaperone (ATOX1) could promote copper transport via ATP7A-LOX signaling, leading to metastasis of breast cancer cells." (PMID 37380924, 2023). "Additionally, an intracellular copper delivery system, modulated by the ATP7A-LOX pathway, can promote tumor growth and metastasis in breast cancer." (PMID 36497253, 2022). "Furthermore, the expression levels of ATP7A and ATP7B in BRCA tissues were slightly higher than those in normal tissues, and the expression of ATP7A and ATP7B in different subtypes of breast cancer was also similar." (PMID 32508020, 2020). "In contrast, ATP7A, DLK1, CRBP1, and SMAD3 were not modulated by aRA in RA-sensitive lung and breast cancer cells." (PMID 16012519, 2005).
ovarian carcinoma (26 papers, 2004 to 2025). A malignant neoplasm originating from the surface ovarian epithelium. "ATP7A silencing lacks impact on resistance, but ATP7A polymorphism is linked to cisplatin resistance in ovarian cancer." (PMID 38434767, 2024). "Another study shows that ATP7A is associated with cisplatin resistance in ovarian cancer and influence effectiveness of treatment with tetrathiomolybdate, which inhibits ATP7A activity." (PMID 36296659, 2022). "The copper efflux transporters ATP7A and ATP7B mediate cisplatin efflux, and overexpression of ATP7A during platinum-based chemotherapy was associated with poor survival in ovarian cancer patients." (PMID 33437029, 2021). "Moreover, lung cancer patients who have higher ATP7A expression exhibit poorer responses to cisplatin-based chemotherapy, and ATP7B and ATP7A are associated with resistance to cisplatin-based drugs in breast and ovarian cancer." (PMID 38305803, 2024). "In esophageal and ovarian cancers, ATP7A is associated with cisplatin resistance." (PMID 36568224, 2022). "These transporters are observed to be upregulated in cisplatin-resistant cancer cells and high levels of ATP7A and ATP7B are associated with significantly poorer overall survival in patients with ovarian cancer and ovarian carcinoma, respectively." (PMID 39124859, 2024). "miR-139 can directly bind to the 3'-UTR of ATP7A/B, contributing to apoptosis induction and increasing the chemosensitivity of ovarian cancer cells." (PMID 38539161, 2024). "Increased expression of the copper efflux transporter ATP7A mediates resistance to cisplatin, carboplatin, and oxaliplatin in ovarian cancer cells." (PMID 36632452, 2023). "The function of circPBX3 upregulation on cisplatin resistance was abolished by downregulation of ATP7A in ovarian cancer cells." (PMID 38152652, 2023). "Previous researches found out that the up-regulated ATP7A was correlated to the platinum drug resistance in colon cancer, esophageal squamous cell cancer, gastric carcinoma, and ovarian cancer." (PMID 35265524, 2022). "Over-expression of ATP7A in ovarian carcinoma 2008 cells resulted in higher levels of Pt drug accumulation upon treatment with the platinum drugs cDDP, CBP and oxaliplatin." (PMID 24086737, 2013). "Samimi G demonstrated that overexpression of ATP7A in human ovarian carcinoma cells confered resistance to DDP, CBDCA and L-OHP by sequestering platinum analogues in intracellular compartments and preventing their reaction with nuclear DNA." (PMID 22304828, 2012). "Three cisplatin-resistant human ovarian carcinoma cell lines exhibited increased expression of one or the other of ATP7A or ATP7B." (PMID 24278698, 2012). "Some studies in ovarian cancer showed similar results that increased expression of ATP7A mediated resistance to platinum derivatives in cancer cells and was associated with poor survival in ovarian cancer patients during platinum drug-based treatments." (PMID 22304828, 2012). "For this purpose, localisation of ATP7A and ATP7B in A2780 human ovarian carcinoma cells and their cisplatin-resistant variant, A2780cis, was investigated." (PMID 18565219, 2008). "Notably, circPBX3 can bind with IGF2BP2 and elevate the stability of ATP7A at mRNA levels, thereby contributing to upregulation of ATP7A protein in ovarian cancer." (PMID 38152652, 2023). "Increased expression of ATP7A led to cisplatin resistance in ovarian cancer cells." (PMID 29301278, 2018). "In addition to ATOX1, investigation of the potential of other copper transporters and chaperones in siRNA therapy of NSCLC and other cancers, such as ATP7B in ovarian cancer and ATP7A in neuroblastoma is warranted." (PMID 23624903, 2013). "Studies on patients with lung and ovarian cancer have indicated that high expression levels of ATP7A are correlated with poor response to CDDP treatments and that of ATP7B have similar outcomes in patients with lung, oral, esophagus, and ovarian cancer." (PMID 31450627, 2019).
ovarian carcinoma (continued). "Since cisplatin transporters can mediate the resistance of ovarian cancer cells to cisplatin, the protein levels of MRP2, ATP7A, ATP7B, and CTR1 in ovarian cancer A2780/CP70 and OVCAR3 cells were evaluated by Western blot analysis." (PMID 29301278, 2018). "In addition, upregulation of the copper efflux transporters ATP7A and ATP7B contributes to chemoresistance in ovarian cancer." (PMID 38539161, 2024). "Moreover, the copper-transporting ATPases ATP7A and ATP7B have been shown to regulate drug resistance in ovarian cancer." (PMID 36950684, 2023). "A detailed analysis of the ATP7A and ATP7B roles in ovarian cancer are discussed in the review." (PMID 36296659, 2022). "Recent data from Howell's lab demonstrated that two P-type of ATPases ATP7A and ATP7B are involved in cisplatin resistance in human ovarian carcinoma cells by modulating cellular pharmacology of cisplatin and other metals, suggesting that a sequestration and secretory system may exist." (PMID 15199393, 2004). "Finally, by analyzing a public gene expression dataset, the same authors found that ovarian cancer patients with elevated levels of hCtr1 in their tumors, but not ATP7A and ATP7B, had more favorable outcomes after treatment with platinating drugs than those expressing low hCtr1 levels." (PMID 24278698, 2012).
colorectal cancer (18 papers, 2012 to 2026). A primary or metastatic malignant neoplasm that affects the colon or rectum. "For instance, abnormal expression of copper transporters ATPase copper transporting alpha/beta (ATP7A/B) is linked to chemotherapy resistance in colorectal cancer (CRC)." (PMID 40236776, 2025). "Increased ATP7A expression protects against excessive copper-induced toxicity in colorectal cancer cells with a mutation in the KRAS gene." (PMID 39408933, 2024). "Dysregulation of SLC31A1, ATP7B, and ATP7A has been implicated in colorectal cancer and can affect copper homeostasis and tumor growth." (PMID 38898987, 2024). "Strikingly, antitumor activity is produced when copper-transporting ATPase 1 (ATP7A) is degraded because this causes an increase in ROS as well as ferroptosis in colorectal cancer cells." (PMID 36733399, 2022). "It was reported that the combined application of the copper chelator elesclomol and copper leads to copper blocking in mitochondria due to the loss of the cuproptosis regulator ATP7A, further enhancing oxidative stress and consequent ferroptosis in colorectal cancer cells." (PMID 36733399, 2022). "Elevated ATP7A expression protects KRAS-mutant colorectal cancer cells from copper toxicity, whereas ATP7A silencing reduces LOX activity and inhibits lung cancer metastasis in mice." (PMID 41480765, 2026). "Elesclomol-induced copper retention within mitochondria promoted oxidative stress and consequent ferroptosis in colorectal cancer cells via copper-transporting ATPase 1 (ATP7A) degradation and ROS accumulation." (PMID 40066457, 2025). "In turn, elesclomol, by promoting copper-dependent ferroptosis, effectively targets colorectal cancer cells through the degradation of the copper transporter ATP7A." (PMID 39857803, 2025). "According to these findings, focusing on ATP7A is a method that can effectively eradicate colorectal cancer driven by the KRAS gene." (PMID 39408933, 2024). "Another research on colorectal cancer revealed that elesclomol also indirectly contributes to intracellular copper aggregation and induced cell death by degrades the copper transporter ATP7A." (PMID 36003780, 2022). "Moreover, in colorectal cancer cells, treatment with the copper ionophore Elesclomol results in reduced ATP7A levels and increased ubiquitination, which impairs copper efflux, promotes mitochondrial copper accumulation, and causes ROS overflow." (PMID 41505058, 2026). "Elesclomol (ES) induces ferroptosis in colorectal cancer (CRC) by degrading ATP7A; ES induces copper chelation, then increases copper levels while reducing ATP7A expression, which leads to reactive oxygen species (ROS) accumulation and promotes the degradation of SLC7A11." (PMID 38200525, 2024). "Plasencia C also reported that ATP7A overexpression in L-OHP resistant colorectal cancer cells." (PMID 22304828, 2012). "It was found that the mutation frequency of each regulator is relatively low, of which ATP7A showed the highest mutation rate, followed by ATP7B and LIPT1, while FDX1, CDKN2A, SLC31A1, and GCSH showed no mutation in all colorectal cancer tissues." (PMID 36248908, 2022).
Alzheimer disease (11 papers, 2011 to 2025). A progressive, neurodegenerative disease characterized by loss of function and death of nerve cells in several areas of the brain leading to loss of cognitive function such as memory and language. "Our results show that ATP7A is associated with steroid hormones, DBT is mainly associated with Alzheimer’s disease, and SLC31A1 is associated with axon guidance, calcium signaling pathways, and Long-term potentiation." (PMID 36338988, 2022).
copper metabolism disorder (10 papers, 2013 to 2025). "ATP7A gene mutations, affecting copper ion transport, are linked to copper metabolism disorders like Menkes and neurodegenerative diseases." (PMID 40520613, 2025). "Subsequently, a copper metabolism disorder caused by dysfunction of the copper transport protein ATP7A, which results from an abnormality of the ATP7A gene on the X chromosome, was identified." (PMID 39717303, 2024). "The ATP7A is an important component of intracellular copper homeostasis, the mutation of ATP7A is closely related to copper transport disorders, also involved in the progression of tumors." (PMID 37885090, 2023). "The concurrent identification of a functional mutation in ATP7A suggests a role for the Menkes gene as a disease modifier in copper-metabolism disorders." (PMID 26747866, 2016). "Although MD, OHS and dHMN are considered distinct phenotypes within the spectrum of ATP7A-related copper transport disorders, phenotypic overlap between MD and OHS has long been recognized." (PMID 41010022, 2025). "Attenuation of copper accumulation by the ATP7A mutation sheds an interesting light on the interplay of copper transporters in body copper homeostasis and warrants a thorough investigation of ATP7A as a modifier gene in copper-metabolism disorders." (PMID 26747866, 2016). "ATP7A seem to be a human disease gene with very variable clinical presentations, and better understanding of these phenotypes may point to mechanistic overlap with other copper metabolism disorders, e.g., aceruloplasminemia." (PMID 27878136, 2016). "In order to develop new treatment strategies for copper-metabolism disorders, several rodent models were investigated, including natural models, such as the mottled mouse, the toxic milk mouse and the Long–Evans cinnamon rat, in addition to ATP7A and ATP7B knockouts." (PMID 26747866, 2016).
neuroblastoma (9 papers, 2013 to 2024). Neuroblastoma (NB) is the most common solid, extracranial childhood tumor. "It is also congruent with a study that showed the interactome of ATP7A immunopurified from neuroblastoma cells is enriched for gene products associated with nervous system diseases and mental disorders." (PMID 39251386, 2024). "We immunoprecipitated ATP7A from cell extracts of cross-linked SH-SY5Y neuroblastoma cells and immunoblotted for proteins of interest." (PMID 28355134, 2017). "We used human SH-SY5Y neuroblastoma cells to perform immunoaffinity chromatography isolation of cross-linked ATP7A complexes." (PMID 28355134, 2017). "Retinoid treatment of neuroblastoma cells causes transcriptional upregulation of ATP7A and an increase in ATP7A protein levels." (PMID 23986700, 2013). "Although we did not detect changes in proliferation, the higher cell densities may have been caused by the inverse relationship between ATP7A expression and proliferation in neuroblastoma cells." (PMID 33151932, 2020). "Finally, we isolated cross-linked ATP7A complexes from SH-SY5Y neuroblastoma cells preincubated in the presence of either CuCl2 or the copper chelator bathocuproine disulphonate (Figures 1C1–2, BCS)." (PMID 28355134, 2017). "Concurrent decrease in hnRNPA2/B1, increase in ATP7A, and a decrease in Cu levels was observed in neuroblastoma SH-SY5Y cells during retinoic acid-induced differentiation; this effect was reversed by overexpression of B1/B1b isoforms." (PMID 36545508, 2022). "We also found that in neuroblastoma SH-SY5Y cells ATP7A abundance increased concurrently with a decrease in hnRNPA2/B1 during cells differentiation to regulate cellular copper levels." (PMID 36545508, 2022). "The mobilization of ATP7A from the surface in the presence of excess copper in HEK293 cells is in contrast with the ATP7A response in SH-SY5Y neuroblastoma cells." (PMID 28355134, 2017). "In order to identify ATP7A-dependent and copper-sensitive mechanisms, we developed an unbiased approach to comprehensively define the ATP7A interactome in neuroblastoma cells." (PMID 28355134, 2017). "High concentrations of copper in neuroblastoma cells are likely achieved via down-regulation of ATP7A expression and thus, reduced copper efflux." (PMID 23986700, 2013). "Consequently, to determine whether hnRNPA2/B1-mediated regulation of ATP7A occurred during neuronal differentiation, SH-SY5Y neuroblastoma cells were differentiated using a two-step protocol using RA and then BDNF treatments." (PMID 36545508, 2022).
distal hereditary motor neuropathy (8 papers, 2013 to 2026). "Finally, specific missense variants in the ATP7A gene are associated with late onset distal spinal muscular atrophy (SMAX3)." (PMID 38141875, 2024). "ATP7A encodes a copper-transporting P-type ATPase and is one of 23 genes in which mutations produce distal hereditary motor neuropathy (dHMN), a group of diseases characterized by length-dependent axonal degeneration of motor neurons." (PMID 31969342, 2020). "Clinical data in patients with ATP7A-related distal hereditary motor neuropathy." (PMID 41010022, 2025). "Among the phenotypes associated with pathogenic ATP7A variants, MD and OHS are the most frequently reported, while ATP7A-related distal hereditary motor neuropathy (dHMN) has only been reported in six families to date." (PMID 41010022, 2025).
distal motor neuropathy (8 papers, 2018 to 2025). "The ATP7A mutation uncovers a UBX domain, supports a novel VCP-ATP7A interaction, and leads to adult-onset isolated distal motor neuropathy." (PMID 37545006, 2023). "SMAX3 exhibits no overt copper metabolic disturbances but is associated with progressive distal motor neuropathy and distal degeneration of axons that spreads to neuronal cell bodies, implicating ATP7A in spinal motor neurons and synaptic function." (PMID 33359139, 2021). "This development, combined with recent descriptions of mutant ATP7A-induced distal motor neuropathies and our current observations regarding ATP7AM1311V, supports a focus on copper regulation as a key mechanism in progressive motor neuron degeneration." (PMID 33359139, 2021). "Despite being genetically related to the previous two diseases, ATP7A distal motor neuropathy, the third member of the ATP7A gene-dependent disease family, does not exhibit any similar biochemical or clinical manifestations besides neurological effects in the form of motor neuron disease." (PMID 39544917, 2024).
lung carcinoma (8 papers, 2012 to 2026). "Loss‐of‐function studies showed that silencing of ATP7A suppresses the growth and metastasis of breast and lung cancer." (PMID 34390123, 2021). "ATP7A is also overexpressed in cisplatin‐resistant nonsmall cell lung cancer (NSCLC) tissues compared with cisplatin‐sensitive NSCLC tissue." (PMID 34390123, 2021). "In lung cancers, ATP7A protein is only expressed in 40% of tumor tissues, and patients expressing ATP7A had a poorer response to platinum-based chemotherapy." (PMID 33271772, 2020). "Despite a potential unexpected result, this analysis indicated a possible implication of p73/ATP7A axis in human lung cancer." (PMID 30530920, 2018). "Our data demonstrate a TAp73-dependent ATP7A transcription control and a possible clinical relevance of this axis for lung cancer patients." (PMID 30530920, 2018). "Bioinformatic analysis of expression profile datasets of human lung cancer patients suggests a possible implication of TAp73/ATP7A axis in human cancer." (PMID 30530920, 2018).